HIF1A (hypoxia inducible factor 1 subunit alpha)
Diseases named in the same sentence as HIF1A in open-access papers (continued):
Sharing a sentence is not in itself a finding about the gene and the disease.
tumor (continued). "While STAT3 can directly regulate several genes that support tumor growth, these effects are compounded by the upregulation of c-Fos and HIF-1α expression." (PMID 24743777, 2014). "In previous tumor studies, the upregulation of miRNA-18a was found to downregulate the levels of HIF-1α, inhibiting angiogenesis in tumor cells." (PMID 25371752, 2014). "Hypoxia inducible factor-1 (HIF-1α) is an important regulatory factor that enables tumor cells to endure a hypoxic microenvironment." (PMID 24669250, 2014). "The expression levels of MMP2 and HIF-1α mRNA and its protein were significantly high when the tumor had a diameter >5 cm, was intrahepatic, exhibited portal metastasis and was of TNM stage III or IV." (PMID 25013467, 2014). "HIF-1α, as the principal molecular signature for hypoxia, is the main downstream regulator of the hypoxic response in tumor cells." (PMID 23723999, 2013). "HIF-1α expression with HPV infection facilitates tumor progression from premalignancy to malignancy." (PMID 23927384, 2013). "Here, we demonstrate that HIF-1α transcript, protein expression and protein nuclear localization are increased in breast ASCs in response to the tumor-derived factor PGE2." (PMID 23566437, 2013). "Recent studies have demonstrated that HIF-1α is expressed in various human malignancies and HIF-1α overexpression is associated with tumor progression, metastasis potential, treatment failure and increased mortality in many malignancies." (PMID 23799043, 2013). "In other words, non-hypoxic signaling of several diverse oncogenes can mimic the effects of hypoxia and HIF1α and sustain the same metabolic phenotype, continuing to offer a growth advantage and apoptosis inhibition in the growing tumor." (PMID 23471124, 2013). "The protein expression of DEC1 and HIF-1α in tumour tissues was 83.8% and 54.3%, respectively, and was significantly higher than that in adjacent normal tissues (83.8% vs 23.7%, P <0.001; 54.3% vs 12.7%, P< 0.001)." (PMID 23445622, 2013). "A series of studies have previously shown that the overexpression of HIF-1α was involved in the pathogenesis of tumor angiogenesis, invasion, metastasis and resistance to chemotherapy." (PMID 23946810, 2013). "Tumors that respond poorly to this type of therapy have increased activation of the hypoxia-induced transcription factor HIF-1α which can enhance tumor survival and progression." (PMID 22684860, 2013). "In support of this strategy, several studies have reported that HIF1α null tumor xenografts show reduced growth, while overexpression of xenograft HIFα promotes increased growth." (PMID 24280044, 2013). "Spearman’s correlation test demonstrated a pronounced positive correlation between HIF-1α expression and tumour malignancy grade (r = 0.59; P < 0.05)." (PMID 24153191, 2013). "The transcriptional activity of HIF-1α is activated by hypoxia, thus triggering a series of adaptive responses leading to glucose metabolism, tumor angiogenesis and erythropoietin generation." (PMID 23251251, 2013). "For example, the HIF1α-driven induction of PDK that occurs in the hypoxic microenvironment in early stages of carcinogenesis is maintained when tumor angiogenesis initiated by HIF1α increases oxygen supply to the growing tumor." (PMID 23471124, 2013). "We used cells transfected with Scrambled-sequence plasmid and eukaryotic expression plasmid to construct transplanted tumors, indicating that survivin downregulation, tumor inhibition and apoptosis induced by HIF-1α miRNA are in accordance with in vitro data." (PMID 23732337, 2013). "So, tumor with HIF-1α overexpression is prone to invasion and metastasis, and associated with poor prognosis." (PMID 23799043, 2013).
tumor (continued). "The relation between primary tumor vascularity and HIF-1α expression in head and neck and oesophageal squamous cell carcinoma has been reported, and the prognostic impact of HIF-1α expression in cancer is varied." (PMID 24165149, 2013). "Following OXi4503 treatment there was an increase in HIF-1α staining in the cytoplasm and nucleus of almost all the surviving tumor cells (1 h and 24 h treated)." (PMID 24403226, 2013). "It has been previously shown that HIF-1α regulates the expression of miR-210 in a variety of tumor types through a hypoxia-responsive element." (PMID 23844087, 2013). "HIF-1α has been reported to activate the transcription of a set of genes which contribute to tumor aggressiveness, including VEGF, ENOI, TGF-α and CXCR4." (PMID 23426939, 2013). "The results showed that Foxp3+ cells mainly assemble in the sites close to hypoxic tumor region with high HIF-1α expression." (PMID 23723999, 2013). "After HIF-1α disrupts cell integrity and membrane, c-Met enhances tumor cell to invade surrounding stroma and migrate into the blood and lymphatic vessels." (PMID 23927384, 2013). "Tumor hypoxia and increased HIF-1α activity can act as major stimuli for tumor aggressiveness and progression." (PMID 23289374, 2013). "HIF-1α and HIF-2α protein is overexpressed in several primary tumours and this is associated with increased patient mortality, indicating that the HIF pathway promotes oncogenesis and/or cancer progression." (PMID 23758895, 2013). "Recent studies have shown that HIF-1α is overexpressed in many human cancers with advanced tumor grade, suggesting that HIF-1α acts as an independent factor of cancer prognosis." (PMID 24260383, 2013). "HIF-1α is upregulated in a wide range of solid tumors in human beings, and overexpression of HIF-1α is associated with tumor aggressiveness and poor prognosis." (PMID 24245510, 2013). "Increased evidence has revealed that HIF-1α overexpression is well correlated with carcinogenesis and tumor progression in many kinds of cancer." (PMID 23799043, 2013). "HIF1α promotes angiogenesis and upregulates metabolic genes, which are necessary to sustain tumor cells." (PMID 24040331, 2013). "The present results provide novel insight into the role elicited by the HIF-1α/GPER transduction pathway in CAFs towards the hypoxia-dependent tumor angiogenesis." (PMID 23947803, 2013). "The correlations between the relative mRNA expression of HIF-1α and pathological characteristics of the tumour sample, such as TNM stage, clinical stage, pathological differentiation grade and smoking and drinking were analysed." (PMID 23599780, 2013). "The resultant hypoxia-endowed tumor cells would have migratory and invasive properties through HIF-1α-induced epithelial-mesenchymal transition." (PMID 23940715, 2013). "Hypoxia inducible factor-1 alpha (HIF-1α), induced by tumor hypoxia, regulates tumor cell metabolism and metastasis by up-regulation of c-Met, carbonic anhydrase 9 (CA9) and glucose transporter 1 (GLUT1)." (PMID 23927384, 2013). "The glycolytic response of hypoxic cells is primarily mediated by the hypoxia inducible factor alpha (HIF-1α) but even in the presence of abundant oxygen tumours typically show high rates of glycolysis." (PMID 23638097, 2013). "The activated HIF-1α results in the up regulation of target genes, which promote tumor cell survival and progression." (PMID 24958263, 2013). "Similar results were obtained by immunostaining of P-gp and HIF-1α in K562 and K562/dx tumor-bearing mice." (PMID 24490156, 2013). "Once stabilised, HIF-1α transactivates a set of downstream genes that, in turn, facilitate tumour growth, angiogenesis and metastasis." (PMID 23599780, 2013). "mTOR interferes with hypoxia-inducible factor-1α (HIF-1α), a key transcription factor with a pivotal role in tumor cell metabolism." (PMID 24216984, 2013).
tumor (continued). "Closer observation of the immunoreactivity for Twist2 and HIF-1α revealed the co-expression of Twist2 with HIF-1α in the tumor cells (r=0.451, P<0.05)." (PMID 23946798, 2013). "Although there is little information in hand to elucidate the mechanism involved in CBF function in tumour tissues, an inhibitory role was still revealed in the blockade of HIF-1α import in CBF-treated xenografts implanted with HCT116." (PMID 23818933, 2013). "Results from our study demonstrated that HIF-1α correlated with a malignant behavior category, including depth of invasion, lymph node metastasis and advancing tumor stage." (PMID 23723999, 2013). "The recognition of the central role of HIF in tumor growth and progression and the in vitro and in vivo demonstration of tumor growth inhibition by many HIF1α inhibitors, is currently translating in clinical trials for some of them." (PMID 23408731, 2013). "A previous study suggested that hypoxia and HIF-1α overexpression contribute to tumor cell invasion and dissemination, probably through activation of MMPs." (PMID 23289374, 2013). "Given the combined VEGF and HIF-1α inhibition appeared to have a synergistic effect on tumor vasculature, we further examined the effect of VEGF-A deprivation plus HIF-1α inhibition on endothelial cells in vitro." (PMID 22684860, 2013). "Human colon cancers xenografted in nude mice treated with the combination of low doses irinotecan and rapamycin showed a potent inhibition of the mTOR/HIF-1α axis, which was accompanied by a dramatic reduction in tumor volume, compared to single agent." (PMID 24216984, 2013). "A study by Chung and colleagues showed that in tumor-derived endothelial cells from VDR knockout mice, loss of VDR resulted in an increase in HIF-1α, VEGF, angiopoietin 1 and platelet-derived growth factor levels." (PMID 24084056, 2013). "Our current data highlight the stimulatory role exerted by the HIF-1α/GPER signaling in the multistep process of tumor neoangiogenesis fostered by CAFs." (PMID 23947803, 2013). "Lymphatic metastasis (P=0.010, P=0.011) and HIF-1α expression (P=0.050, P=0.030) were also predictors of tumor-free survival in multivariate regression." (PMID 23251251, 2013). "It has been demonstrated that HIF-1α is overexpressed in many human tumor types, and its overexpression is induced by hypoxia and by oxygen-independent mechanisms." (PMID 23326384, 2013). "There is increasing evidence that tumor cells often reside in a low oxygen tension environment that promotes accumulation of HIF-1α and is involved in tumor progression and aggressiveness." (PMID 23289374, 2013). "Tumor hypoxia and increased hypoxia-inducible factor-1α (HIF-1α) activity can act as major stimuli for tumor aggressiveness and progression." (PMID 23289374, 2013). "Simple cysts, atypical cysts and neoplasms all displayed high nuclear immunoreactivity for HIF1α and HIF2α verifying that these lesions are derived from Vhl null cells." (PMID 23606570, 2013). "Selective genetic or pharmacological inhibition of eNOS or iNOS or enzymatic induction of NO deficiency in tumor cells diminishes VEGF, HO-1, and HIF1α activation and consequent tumor cell proliferation and angiogenesis." (PMID 23964349, 2013). "Immunohistochemical studies on human tumours demonstrated pronounced expression of HIF-1α in many common tumours, which probably represents a consequence of both hypoxia within the tumour and various genetic disturbances in neoplastic cells." (PMID 24153191, 2013). "This is in keeping with previous work showing that inhibition of PDK with short-hairpin RNA decreases HIF1α activity and tumor growth in squamous cell carcinoma." (PMID 23471124, 2013). "The mRNA expression levels in fresh tissues obtained from 2 cases were observed, demonstrating that HIF-1α mRNA was highly expressed in the tumor tissue but expressed at a low level in the adjacent tissue." (PMID 23251251, 2013).
tumor (continued). "While VEGF inhibition with sunitinib of human-derived tumor spheroids in an in vivo model was found to decrease tumor enhancement while increasing proportion of infiltrating cells, the HIF1-α pathway is activated in the process." (PMID 23634286, 2013). "We next explored the effects of DC101 along with HIF-1α inhibition (either with HIF-1α shRNA or metronomic Dox) on tumor vasculature." (PMID 22684860, 2013). "It has been reported that targeting HIF-1α signalling in tumour cells significantly inhibits tumour growth in mouse xenografts." (PMID 23599780, 2013). "After A549 cells were xenografted in nude mice, survivin expression in mice treated with HIF-1α miRNA was downregulated, and tumor growth was significantly inhibited." (PMID 23732337, 2013). "Increased Hif-1α protein levels in primary tumor biopsies correlates with poor outcome in breast, ovarian, pancreatic, bladder, colorectal and lung cancer among others." (PMID 23840457, 2013). "In adenocarcinomas, over 39% tumours manifested HIF-1α expression evaluated at +, over 26% expression evaluated at ++ and 25% at +++." (PMID 24153191, 2013). "HIF-1α also facilitates disruption of basement membrane and extracellular matrix which are physical barriers against tumor cell migration." (PMID 23927384, 2013). "HIF-1α is regulated in cellular responses and plays an important role in angiogenesis and tumor progression." (PMID 23936001, 2013). "HIF-1α with low expression (upper) and high expression (down) was found predominantly in the cytoplasm and nucleus of cancer cells at the tumor margin, and only nuclear HIF-1α staining was scored." (PMID 23723999, 2013). "HIF-1α, an important transcriptional factor, promotes tumor angiogenesis by upregulating different angiogenic genes." (PMID 23819061, 2013). "In our studies, we found that Poly-SNO-HSA possesses very strong HIF-1α inhibition in tumor cells in vivo." (PMID 24490156, 2013). "HIF-1α and hypoxia are the principle determining factors of angiogenesis and they regulate the process of invasion and metastasis, which determines the tumor aggressiveness." (PMID 23326384, 2013). "Preclinical studies have demonstrated that HIF-1α inhibition suppresses angiogenesis and tumor growth and its suppression enhances treatment outcomes when used in combination with chemotherapeutic agents and radiation." (PMID 24312289, 2013). "A similar trend was also found between the expression of HIF-1α (P<0.001) or Foxp3 (P = 0.008) and tumor stage." (PMID 23723999, 2013). "In clinical studies, elevated expression of HIF-1α was found to correlate with lymph node involvement, tumour-node-metastasis (TNM) classification, poor survival and resistance to chemo- and radiotherapy in patients with oral squamous cell carcinomas." (PMID 23599780, 2013). "Basic and clinical researches have confirmed that the expression level of HIF-1α, as well as absolute low pO2, correlates with a poor prognosis and incidences of both tumor recurrence and distant tumor metastasis after radiation therapy." (PMID 23509762, 2013). "VGEFs can be produced both by activated leukocytes and mesenchymal cells present in the tumor microenvironment or, more importantly, by tumor cells themselves under the influence of activated HIF1α and NFkB." (PMID 23408731, 2013). "MEL decreased the EGF-induced hypoxia-inducible factor-1α (HIF-1α) protein and significantly regulated angiogenesis and tumor progression." (PMID 23936001, 2013). "By contrast, there were only 5 (33.33%) cases of weak expression of HIF-1α in the 15 adjacent non-tumor tissue specimens." (PMID 23251251, 2013). "The effects of pH and hypoxia on CA IX and HIF-1α protein level expression and their relationship to tumor invasiveness were also studied using immunofluorescence with in vitro cell culture." (PMID 23914349, 2013). "In contrast, overexpression of miR-20b in hypoxic tumor cells can decrease the protein levels of HIF-1α and VEGF." (PMID 23951172, 2013).
tumor (continued). "HIF-1α has previously been demonstrated to perform a vital role in modulating the biological characteristics of tumor cells, including angiogenesis, unlimited growth and resistance to chemotherapy." (PMID 23946810, 2013). "Our results strongly indicate that the mechanism through which CI regulates the glycolytic shift is mediated by HIF-1α stabilization, allowing tumor cells to adapt to hypoxia and persist in proliferation." (PMID 24280190, 2013). "Excess HIF-1α can promote several important aspects of cancer biology, including the metabolic switch to anaerobic glycolysis characteristic of tumor cells [i.e. the Warburg effect; 26], neoangiogenesis, and increased tumor metastasis [reviewed in 13]." (PMID 23459416, 2013). "VEGF expression within tumor cells is under the control of a number of essential transcription factors, one of the most important being HIF-1α, which regulates survival genes, including VEGF." (PMID 23123638, 2013). "Currently, there is no shortage of controversy with regard to a correlation between HIF-1α expression and the tumor progression and lymph node metastasis of LSCC." (PMID 23946810, 2013). "HIF-1α levels remained high mainly in the tumor cytoplasm at day five despite reduction in hypoxia staining (5 day treated)." (PMID 24403226, 2013). "Tumor adaptation to hypoxia is predominantly regulated by HIF-1α and HIF-2α, which activate the expression of genes involved in proliferation, metabolism, angiogenesis, and metastasis." (PMID 24288553, 2013). "The mRNA analysis of tumour tissues showed that HIF-1α mRNA level was dramatically elevated in i.p. group." (PMID 23818933, 2013). "HIF1α and NFkB are two transcription factors very frequently activated in tumors and involved in tumor growth, progression, and resistance to chemotherapy." (PMID 23408731, 2013). "Tumor HIF-1α protein levels were undetectable by Western blot in BAY 87-2243-treated xenograft tumors in contrast to the vehicle-treated tumors." (PMID 24403227, 2013). "During tumor angiogenesis, the activation of hypoxia-inducible factor-1α (HIF-1α) in hypoxia cells firstly triggers vascular endothelial growth factor (VEGF) expression, which stimulates vascular growth within hypoxic tumor tissues." (PMID 23951172, 2013). "Inhibition of VEGF signaling in tumor cells directly induced malignant phenotypes through, at least in part, HIF-1α up-regulation." (PMID 23651517, 2013). "Values of HIF-1α and CA IX were used as the indicator of tumor hypoxia, and their intensities were divided into four groups according to the combination of α-SMA and MVD." (PMID 23940715, 2013). "Overexpression of miR-199a/125b dramatically downregulates HIF-1α protein expression as well as VEGF mRNA levels, suggesting that miR-199a/125b suppresses tumor angiogenesis by decreasing the expression of HIF-1α and VEGF." (PMID 23437196, 2013). "Plk3 can also phosphorylate and stabilize PTEN phosphatase, a known regulator of HIF-1α and tumor angiogenesis." (PMID 23327547, 2013). "HIF-1α is one of the major factors responsible for orchestrating the adaptive transcriptional programs, inducing cell survival, motility and tumor angiogenesis under hypoxic conditions." (PMID 24204703, 2013). "Still, HIF1A can protect tumor cells from hypoxia to survive and grow by the means of promoting proliferation, becoming resistant to apoptosis, switching to a glycolytic metabolism, evading immune attack, migrating to less hypoxia areas of the body, and so on." (PMID 23723982, 2013). "Under normoxic conditions, cancer cell lines, like their tumours of origin, usually show an increased proportion of energy derived from glycolytic processes together with higher levels of HIF-1α." (PMID 23638097, 2013). "Western blotting assay further demonstrated that both LDH-A and HIF-1α expression were down-regulated in EGC-treated tumor samples, which is consistent with immunohistochemistry results." (PMID 23457597, 2013).